HOTAIR (HOX transcript antisense RNA)
Diseases named in the same sentence as HOTAIR in open-access papers (continued):
Sharing a sentence is not in itself a finding about the gene and the disease.
breast cancer (continued). "Besides, experiments have demonstrated that treatment of breast cancer MCF-7 cells with genistein resulted in decreased phosphorylation of Akt, and decreased expression of HOTAIR." (PMID 34482818, 2021). "lncRNAs involved in breast cancer cell drug-resistance are UCA1 in doxorubicin resistance, PANDA in anthracycline resistance, ARA in adriamycin resistance, CCAT2 in 5-fluorouracil, and BCAR4, HOTAIR, and M41 in tamoxifen resistance." (PMID 34123857, 2021). "Furthermore, HOTAIR induces selective re-targeting of PRC2 and trimethylated H3K27 genome-wide, thus promoting the invasion of breast cancer cells." (PMID 32486413, 2020). "The important role of HOTAIR in metastasis raises the question whether there is any potential correlation between this lincRNA and EMT in breast cancer patients?" (PMID 32245498, 2020). "Negative impact of hyperactivity of HOTAIR has been shown on regulation of miR-141 and miR-326 in glioma cells, as well as suppression of miR-141 in breast cancer cells." (PMID 32245498, 2020). "Thus, the interdependence between HOTAIR and PRC2 has therapeutic implications for breast cancer metastasis." (PMID 32929060, 2020). "Additionally, HOTAIR up-regulates expression of SNAIL, as a master regulator of EMT pathway, in breast cancer." (PMID 32245498, 2020). "In the triple negative and ER+ breast cancer cells, E2-GPER signal promotes HOTAIR expression." (PMID 32245498, 2020). "Similarly, TGF-β1 secreted by CAFs upregualted lncRNA HOTAIR expression to promote EMT and metastasis in breast cancer." (PMID 31448238, 2019). "Curiously, no significant expression level of HOTAIR was determined in the breast cancer patients’ peripheral blood, before and after radiotherapy (10 Gy exposure)." (PMID 31796041, 2019). "Findings showed no significant expression level of HOTAIR transcription, while HOTAIR circulatory DNA was almost duplicated in the serum of breast cancer patients compared to the normal individuals." (PMID 31796041, 2019). "Methylation of C1683 was found to be invariable, regardless of the different levels of HOTAIR expression and the different types of cancer cells, such as Hs578T and BT-20 breast cancer and HOC7 ovarian cancer cell lines." (PMID 30654440, 2019). "Curiously, analysing the data from the “Expression Atlas Biobank of European Bioinformatics Institute” also proposed no significant to very low HOTAIR transcript level in not only normal individuals’ but also breast cancer patients’ peripheral blood." (PMID 31796041, 2019). "Not all the different isoforms of HOTAIR have been characterized, even if the aberrant activation of the promoter region upstream of HOTAIR-N has been mainly implied in invasive breast cancer." (PMID 31072041, 2019). "Here, Ren and colleagues demonstrate that the TGFβ1/HOTAIR axis, by targeting CDK5 signaling, promotes the metastatic capacity of breast cancer cells, thus suggesting that its targeting may be considered a novel strategy for the treatment of breast cancer." (PMID 30927908, 2019). "Moreover, it was recently reported that HOTAIR influences cell metastasis and apoptosis through miR-20a-5p/HMGA2 signaling in breast cancer." (PMID 31481088, 2019). "Our previous study proved that the 5′ domain, but not its 3′ domain, was the function domain of HOTAIR responsible for tumorigenesis and metastasis in glioblastoma and breast cancer, by recruiting and binding EZH2." (PMID 30764859, 2019). "Intriguingly, HOTAIR serves as an independent predictor of metastasis in patients with ER+ breast cancer but not in patients with ER- breast cancer." (PMID 29732012, 2018). "HOTAIR was also demonstrated to suppress the tumor inhibitor miR-7 by regulating the expression of HoxD10, thereby sustaining the expression levels of c-myc, TWIST and miR-9 and maintaining the EMT process and the CSC pool of breast cancer." (PMID 29299179, 2017). "In breast cancer, TGFβ1 treatment induces EMT via HOTAIR expression." (PMID 28931862, 2017).
breast cancer (continued). "HOTAIR recruits polycomb repressive complex (PRC2) to specific targets genes promoter regions, leading to H3K27 trimethylation and epigenetic silencing of metastasis suppressor genes, and to increasing breast cancer invasiveness and metastasis." (PMID 27613832, 2016). "Of note, HOTAIR expression in UC cell lines was not quite as high as in the mammary cancer cell line MCF7, which was used as a control for very high expression." (PMID 25994132, 2015). "To further follow the indications that HOTAIR action might be cell type-dependent, we compared our results to those of others, especially to those for HOTAIR-overexpressing MDA-MB231 breast cancer cells." (PMID 25994132, 2015). "In addition, we found that estrogen promoted HOTAIR through its receptor GPER and estrogen-induced breast cancer cell migration was reversed by deleting HOTAIR in TN breast cancer cells MDA-MB-231and BT549." (PMID 25928008, 2015). "Recent studies have shown that HOTAIR could inhibit miR-7 expression, resulting in the up-regulated SETDB1 expression and promoted epithelial-mesenchymal transition (EMT) in breast cancer stem cells." (PMID 26183397, 2015). "In addition, we found that estrogen promoted HOTAIR through its receptor GPER and estrogen-induced breast cancer cell migration was reversed by deleting HOTAIR." (PMID 25928008, 2015). "Preventing the interaction between HOTAIR and the PRC2 or LSD1 complex may limit the metastatic potential of breast cancer cells." (PMID 25422887, 2014). "HOTAIR and BC200 are upregulated in breast cancer as well as in other cancers." (PMID 25400658, 2014). "Those lncRNAs include some already known to be involved in cancer, such as H19 and HOTAIR, as well as novel lncRNAs never reported in breast cancer (e.g., HOTAIRM1)." (PMID 25296969, 2014). "Interestingly, ablation of HOTAIR expression by siRNA prevented the EMT program stimulated by TGF-β1, as well as the colony forming capacity of colon and breast cancer cells." (PMID 25334066, 2014). "Preventing the interactions of HOTAIR with the PRC2 or LSD1 complexes, for example, may limit the metastatic potential of breast cancer cells." (PMID 21489289, 2011). "In addition, NF-κB signaling is influenced by lncRNAs such as HOTAIR and MEG3 in breast cancer." (PMID 39858015, 2025). "However, there are additional emerging lncRNAs that have been described as potential biomarkers in cancer, such as HOTAIR, DSCAM-AS1, and GATA3-AS1 in breast cancer, MALAT1 in lung cancer, H19 in colorectal cancer, HULC in liver cancer, UCA1 in bladder cancer, and DLEU1 in endometrial cancer." (PMID 37108589, 2023). "The results showed that five lncRNAs including HOTAIR, DANCR, PVT1, LINC00511, and NEAT1 and 16 miRNAs and five of their targets—VEGFA, BTG2, E2F3, IRAK1, and SMAD4—have significantly different expression patterns in normal individuals compared to those with breast cancer." (PMID 36726376, 2023). "Exogenous overexpression of HOTAIR in the MDA-MB-231 triple-negative breast cancer (TNBC) cell line results in the repression of hundreds of genes, and it promotes cell invasion, migration, proliferation, and self-renewal capacity in multiple breast cancer cell lines." (PMID 36441764, 2022). "A recent study showed that HOTAIR is able to work independent of PRC2 in a breast cancer cell line." (PMID 33891491, 2021). "For instance, HOTAIR is a miR-148a sponge that regulates Slug to promote EMT expression in esophageal cancer, lincRNA-ROR induces EMT through ZEB regulation by inhibition of miR-205 in breast cancer and H19 operates as a sponge for let-7 to increase HMGA-2 mediated EMT in pancreatic cancer." (PMID 32575745, 2020). "Breast cancer gene 1 (BRCA1) is able to inhibit the binding of EZH2 to HOTAIR and its transfer on the promoter of PRC2 target gene HOXA9 in human BC cells and fibroblasts." (PMID 32397382, 2020).
breast cancer (continued). "Furthermore, Up-regulation of HOTAIR and methylation of HOXA5 were found during the development of breast cancer and a previous study indicated that HOTAIR and homeobox A5 (HOXA5) worked together and were closely correlated to growth and metastasis of non-small cell lung cancer." (PMID 31168296, 2019). "HOTAIR also silences miR-568 via recruitment of both EZH2 and LSD1 to the miR-568 promoter in breast cancer cells, leading to derepression of the miR-568 target NFAT5, which induces of EMT and invasion in breast cancer via transcriptional activation of calcium binding protein S100A4." (PMID 28430163, 2017). "HOTAIR expression has been found to be necessary for the maintenance of the CSC phenotype in colon and breast cancer cell lines, and has recently been shown to regulate the breast cancer CSC population by transcriptionally inhibiting miR-34a, resulting in the upregulation of SOX2." (PMID 28430163, 2017). "We sought to determine if expression of HOTAIR could be used as a surrogate for assessing nodal metastases and evaluated RNA in situ hybridization (RNA-ISH) assay in a tissue microarray constructed from 133 breast cancer patients." (PMID 25739705, 2015). "We observed that many of the top CpGs mapped to PCGTs and found that PCGTs (defined as PRC2 targets in both human embryonic stem cells and human embryonic fibroblasts, but not PRC2 targets in breast cancer cells) were highly enriched among CpGs hypermethylated in HOTAIR expressors." (PMID 26497652, 2015). "In addition, we also compared the differential expression of HOTAIR in the PBMCs and breast cancer tissues from the patients with migrated breast cancer and non-migrated breast cancer." (PMID 25928008, 2015). "Moreover, simultaneous up-regulation of HOTAIR and EZH2 might be of clinically significance because a recent study of a breast cancer archive correlates simultaneous high expression of EZH2 and HOTAIR with aggressive tumor growth and metastasis." (PMID 26378045, 2015). "Levels of HOTAIR have been reported to be fourfold higher in colon and breast cancer stem cell-like cells (CD133+/CD44+) compared to non-stem cell-like cells (CD133−/CD44−), and its down-regulation reduced the number and size of colonies assessed by anchorage-independent growth." (PMID 24971229, 2014). "Thus, preventing the interactions of HOTAIR with PRC2, for example, may limit the metastatic potential of breast cancer cells." (PMID 23887658, 2013). "Importantly, it has been shown that BRCA1 (breast cancer early-onset 1) protein binding to PRC2 inhibits the binding of HOTAIR to the EZH2 component of PRC2, and abolishes HOTAIR-enhanced recruitment of PRC2 to its target HOX (homeobox) A9 gene promoter in human breast cancer cells and fibroblasts." (PMID 23875687, 2013). "In order to determine if all three lncRNA HOTAIR, ncHoxA1, and ncHoxD4 co-express with EZH2, and to help determine the roles of both the lncRNA and Polycomb protein in breast carcinoma, EZH2 protein immunohistochemical staining was performed on the breast carcinoma microarrays." (PMID 23133536, 2012). "In addition, a group of researchers detected the serum levels of lncRNAs PVT1, HOTAIR, NEAT1, and MALAT1 from Egyptian breast cancer and fibroadenoma patients, as well as healthy donors, and found that serum PVT1, HOTAIR, and NEAT1 could serve as potential biomarkers for breast cancer." (PMID 38505593, 2024). "Abba and colleagues observed an increased expression of HOTAIR between normal breast cancer and DCIS in vitro but did not observe a significant increase when comparing DCIS with IBC, suggesting that alterations in this lncRNA may be an early event in breast tumorigenesis." (PMID 37240077, 2023). "However, another study demonstrated that the oncogenic role of HOTAIR in breast cancer cells may be independent of PRC2." (PMID 34527584, 2021). "Also, HOTAIR, NEAT1, PAI-1, and OPN could discriminate between breast cancer and fibroadenoma." (PMID 33670447, 2021).
breast cancer (continued). "Moreover, HOTAIR functions as a ceRNA for miR-20a-5p and upregulates a miR-20a-5p target, the high mobility group AT-hook 2 (HMGA2) gene, which enhances the proliferation, survival, migration, and invasion of breast cancer cells, and the growth of breast tumors." (PMID 32486413, 2020). "However, how HOTAIR is involved in trastuzumab resistance in breast cancer has not been reported." (PMID 31882666, 2019). "However, a more recent study showed that the repressing activity of HOTAIR in breast cancer cells does not require PRC2 and that the recruitment of this complex is instead a consequence of gene silencing that is established by the lncRNA with a still not defined mechanism." (PMID 29443889, 2018). "PRC2 is not required for HOTAIR to tether to chromatin, and HOTAIR-mediated transcriptional repression has been reported in PRC2-depleted breast cancer cells." (PMID 35905723, 2022). "In contrast, the expression levels of HOTAIR and NEAT1 were not significantly altered in breast cancer patients." (PMID 33670447, 2021). "The qPCR analyses revealed that neither total HOTAIR RNA nor cytoplasmic and nuclear HOTAIR RNA levels were significantly changed after AQB treatment in glioblastoma and breast cancer cells." (PMID 31367244, 2019). "Interestingly, miR-7, which is inhibited by HOTAIR through the suppression of HoxD10, is downregulated in breast cancer CSCs and overexpression of miR-7 could both partially reverse EMT and decrease the size of the CSC population in breast cancer cell lines by suppressing STAT3 signalling." (PMID 28430163, 2017). "Although the steady levels of HOTAIR are similar in TNBC-like and non-TNBC breast cancer cell lines, induction of β-catenin function preferentially stimulate HOTAIR expression in TNBC-like cell lines compared with non-TNBC cell lines." (PMID 25883211, 2015). "The lncRNA HOX Transcript Antisense RNA (HOTAIR), which regulates the transcriptional silencing of EZH2 and the epigenetic modification of H3K27, is reported as a negative prognostic factor in breast cancer and colon cancer." (PMID 33329315, 2020). "However, like HOTAIR as of yet there is no direct link of SOX2OT involvement in mammary gland development, but due to their critical roles in embryonic development and links to breast cancer they have included here." (PMID 29732012, 2018).
gastric cancer (172 papers, 2013 to 2025). A primary or metastatic malignant neoplasm involving the stomach. "According to other studies, HOTAIR functions as a trans-acting lncRNA and is linked to stomach cancer." (PMID 38294554, 2024). "The TT genotype in HOTAIR rs920778 has been associated with increased HOTAIR expression in esophageal normal tissue, cervical cancer and normal tissues, and gastric cancer and normal tissues." (PMID 38275875, 2024). "LncRNA HOTAIR polymorphism rs4759314 is located in the intronic promoter region, changes promoter activity, and contributes to potential mechanisms for gastric cancer susceptibility by affecting the expression of HOTAIR and HOXC11 genes." (PMID 37337955, 2023). "Here we aimed to investigate the expression of MEG3 and HOTAIR in gastric cancer tissues and evaluate their association with the H. pylori status." (PMID 35186192, 2022). "HOTAIR upregulation appears closely associated with clinic-pathological characteristics and tumor progression in colorectal cancer and gastric cancer." (PMID 33540611, 2021). "HOTAIR is widely studied as an oncogene, and functional SNPs of HOTAIR have been related to cancer risk, including lung cancer, gastric cancer, esophageal cancer, cervical cancer and, prostate cancer, among others." (PMID 34322392, 2021). "Previous studies have pointed out the genotype-specific effect of the rs12826786 SNP on HOTAIR expression in gastric cancer and the association between the rs4759314 minor allele and high HOTAIR transcription in prostate cancers." (PMID 34395618, 2021). "In this research, ISH was performed to explore the expression of HOTAIR and miRNA‐206 in gastric carcinoma and adjacent tissues, associated with corresponding correlation analysis." (PMID 33473276, 2021). "This study aimed to assess the associations of lncRNA ANRIL, H19, MALAT1, MEG3, HOTAIR single-nucleotide polymorphisms (SNPs) with gastric cancer and atrophic gastritis." (PMID 33333725, 2020). "This study aimed to examine associations of lncRNA ANRIL (rs17694493, rs1333045, rs1011970), H19 (rs217727), MALAT1 (rs3200401), MEG3 (rs1054000), and HOTAIR (rs17840857) polymorphisms with gastric cancer and atrophic gastritis in European population." (PMID 33333725, 2020). "The overexpression of HOTAIR in gastric cancer is an effective predictor of tumor progression, associated with venous invasion, lymph node metastasis, and shortened survival in patients with diffuse gastric cancer." (PMID 32695786, 2020). "The studies have shown the association between high HOTAIR expression and poor survival in gastric cancer patients." (PMID 33333725, 2020). "High expression of HOTAIR reveals closely association with cancers, such as gastric cancer, lung cancer and CRC." (PMID 31694696, 2019). "HOTAIR overexpression was also connected with gastric cancer malignancy and survival outcome in a study that linked the upregulation of HOXC cluster genes with high-risk gastrointestinal stromal tumours." (PMID 29685978, 2018). "GAS5 has already been reported to be associated with the occurrence of gastric cancer, and HOTAIR has also been reported on by us." (PMID 28077118, 2017). "In conclusion, the results indicated that HOTAIR polymorphism rs920778 was more generally associated with cancer risk, particularly in Asians, while rs4759314 was a risk factor for gastric cancer." (PMID 27246974, 2016). "High expression of HOTAIR associated with advanced stage, lymphatic node metastasis and poor survival was also reported in gastric cancer." (PMID 25954300, 2015). "For GC, the HOTAIR level was highly expressed and significantly associated with gastric cancer progresses and prognosis." (PMID 26384301, 2015). "HOTAIR is mechanistically linked to increased gastric cancer cell metastasis via dependent of miR34a." (PMID 26136075, 2015). "The increased expression of HOTAIR in human gastric cancers was associated with venous invasion, lymph node metastases and a lower overall survival rate." (PMID 25496320, 2014).